BRAF (B-Raf proto-oncogene, serine/threonine kinase)
Diseases named in the same sentence as BRAF in open-access papers (continued):
Sharing a sentence is not in itself a finding about the gene and the disease.
melanoma (continued). "Here, we show that blood bilirubin in patients with BRAF-mutant melanoma treated with vemurafenib is negatively correlated with clinical outcomes." (PMID 34222023, 2021). "We tested the effectiveness of the vemurafenib and carmofur combination compared with vemurafenib alone for treating BRAF-mutant melanoma in vivo." (PMID 33766731, 2021). "Over the past few years, the prognosis of patients with advanced melanoma has been improved by the use of programmed cell death antibody 1 (PD-1), anti-cytotoxic antibody protein 4 associated with T-lymphocytes (CTLA-4), BRAF inhibitors, and MEK inhibitors." (PMID 34681580, 2021). "EGFR is a well-studied oncogene in lung cancers and gliomas, MET is also a frequent driver in lung cancers, and BRAF is a signature driver gene in melanoma." (PMID 34054918, 2021). "One potential target of miR-129-5p is SOX4, which was reported to induce cell proliferation and to mediate BRAF inhibitor resistance in melanoma." (PMID 34063443, 2021). "RSK inhibition with BI-D1870 and BRD7389 resulted in a significant reduction of protein synthesis and proliferation in dual-resistant melanoma cell lines to BRAF and MEK inhibitors." (PMID 33807778, 2021). "This novel investigation used glucocorticoids in mice inoculated with BRAF V600E melanoma and found that the steroid addition overcame BRAFi resistance." (PMID 33807778, 2021). "The overall frequency of main mutations in mucosal melanomas is as follows: NRAS (8%), BRAF (6%), neurofibromin 1 (NF1) (14%), KIT (13%), splicing factor 3b subunit 1(SF3B1) (15%)." (PMID 35008570, 2021). "Patients with BRAF wild-type melanoma and a performance status (PS) of 0 showed better response rates than patients without these conditions, but the difference in the ORR was not statistically significant." (PMID 34115870, 2021). "It was observed that Vemurafenib, a BRAF inhibitor, alters the miRNA expression in melanoma cells, leading to an upregulation of miR-181a-2-3p." (PMID 34698264, 2021). "The CUL1(e7)–BRAF(e9) fusion was previously observed in a few cases of melanoma and low-grade serous carcinoma (LGSC), and only once in CRC." (PMID 34657620, 2021). "In the 100 patients with BRAF mutant melanoma, the median survival for first line Dabrafenib and Trametinib was 17.4 months." (PMID 34677256, 2021). "miR-514a-3p was further described to regulate the tumor suppressor NF1 and to be involved in BRAF inhibitor sensitivity in melanoma." (PMID 34073664, 2021). "Despite including 21 international sites, we were only able to recruit a modest number of patients, though this is expected given the relative infancy of adjuvant therapy in melanoma and the necessity to include BRAF mutant patients only." (PMID 33087895, 2021). "The RAF family of kinases consists of ARAF, BRAF, and CRAF, with BRAF mutations commonly occurring in papillary thyroid cancers, melanomas, and hairy cell leukemias." (PMID 34299488, 2021). "Resistant melanoma cells displaying enhanced migratory and pro-invasive abilities increased sensitivity to the BRAF inhibitor PLX4032 upon the molecular targeting of FASN and upon treatment with the FASN inhibitor orlistat." (PMID 34068792, 2021). "We evaluated BM incidence in melanoma patients receiving immune checkpoint inhibitors (ICI) or anti-BRAF therapy and identified prognostic factors for overall survival (OS)." (PMID 34503304, 2021). "Understanding that these BRAF mutations are likely driven by UV mutagenesis and often result in OIS is important for the prevention and treatment of melanoma." (PMID 34066966, 2021). "Vemurafenib (PLX4032), a compound selectively inhibiting BRAF V600E, showed positive clinical effects in melanoma." (PMID 34702444, 2021). "For instance, paradoxical activation of the fibroblastic stroma in BRAF inhibitor treated melanomas resulted in enhanced matrix remodelling." (PMID 34459009, 2021).
melanoma (continued). "BRAF-driven melanomas with high mitochondrial content exhibit increased oxidative phosphorylation when treated with BRAF inhibitors and are more sensitive to mitochondrial-targeted drugs." (PMID 34567159, 2021). "Introduction of miR-181 mimics markedly decreases the expression of TFAM in A375 melanoma cells resistant to BRAF inhibitors." (PMID 33670365, 2021). "About 50% of melanomas harbor oncogene BRAF mutations able to activate the MAPK pathway, which regulates a melanoma cell’s proliferation, growth and survival." (PMID 35008245, 2021). "The BRAF mutation, together with the RAS mutation, are strictly correlated with the high Extracellular Signal Related Kinases (ERK) activity in melanoma." (PMID 34683910, 2021). "In the context of BRAF (V600E) mutations, NF1 has been observed to disrupt normal MAPK and PI3K pathways by inhibiting the development and the metastatic spread of melanoma." (PMID 34203771, 2021). "The tumorigenesis of melanoma is associated with several gene mutations in BRAF, NRAS and C-KIT, which are correlated with the histopathological characteristics of melanoma." (PMID 34069297, 2021). "Binimetinib (Mektovi, BNB), a MEK inhibitor, and encorafenib (Braftovi, ENF), a BRAF inhibitor, are two orally bioavailable drugs established by Array BioPharma that are used for treating melanoma." (PMID 34063139, 2021). "A mechanism of acquired resistance in BRAF-mutant melanoma involves overexpression of YAP, a component of the Hippo pathway, whose upregulation is mediated by BET bromodomain proteins." (PMID 34440824, 2021). "This was expected because PLX is known to inhibit BRAF-mutant melanoma cell proliferation by inducing G1 cell cycle arrest with few apoptosis-related activities." (PMID 33810045, 2021). "The important oncogenic role of the mutant BRAF gene expression makes it a suitable target for the treatment of melanomas through siRNA-mediated gene silencing approaches." (PMID 34723284, 2021). "A classic example is resistance to BRAF inhibitors in patients with melanoma, characterized by the paradoxical activation of the MAPK pathway due to increased formation of RAF homo- and hetero-dimers, particularly BRAF-CRAF heterodimers." (PMID 34944932, 2021). "In 2011, the first selective inhibitor of mutated BRAF, vemurafenib, was approved by the US Food and Drug Administration for treating BRAF-mutant metastatic or unresectable melanoma." (PMID 34621046, 2021). "For advanced stage or unresectable melanoma, systemic therapies, including chemotherapy, immune checkpoint blockers, and target therapies with BRAF/MEK or KIT inhibitors, are necessary." (PMID 33809137, 2021). "At the post-translational level, tyrosine kinase ACK1, which is downregulated in some BRAF inhibitor-resistant melanomas, induces EGFR turnover." (PMID 33916908, 2021). "The combination of dabrafenib and trametinib is an important therapy for patients with BRAF-mutant melanoma." (PMID 34590600, 2021). "Monotherapy with ipilimumab tends to be replaced by nivolumab and pembrolizumab due to its toxicity with an exception for BRAF wild type melanoma, which seems to respond better to ipilimumab." (PMID 33672017, 2021). "In this study we investigated the antitumoral mechanism of action of an octopus-derived peptide (Octpep-1) in BRAF(V600E) melanoma cells." (PMID 33672955, 2021). "BRAF ± MEK inhibition has been shown to induce very rapid responses in the majority of metastatic BRAF-mutant melanomas." (PMID 34743688, 2021).
melanoma (continued). "Here we track the responses of thousands of single melanoma cells to BRAF inhibitors and show that a subset of cells escapes drug via non-genetic mechanisms within the first three days of treatment." (PMID 33741929, 2021). "As such, a number of MAPK pathway drugs have been developed, such as MEK and BRAF inhibitors which are most commonly used to treat human melanoma." (PMID 33526843, 2021). "In the CheckMate 066 trial, the 5-year overall survival rate was 39% with nivolumab, 17% with dacarbazine, and 38% with dacarbazine and subsequent therapy, including nivolumab in patients with wild-type BRAF advanced melanoma." (PMID 34804979, 2021). "BRAF inhibitor resistance in melanoma seems remarkably adaptable, as there are so many diverse mutations that have been reported." (PMID 34831420, 2021). "Taken together, these findings demonstrate that bilirubin can effectively block the growth inhibition effects of vemurafenib on BRAF V600 mutant melanoma in cell lines and xenograft models." (PMID 34222023, 2021). "Examining the role of IGF1R and IR in mediating resistance to BRAF and MEK inhibitors will expand possible treatment options to aid in long-term success for BRAF-mutant melanoma patients." (PMID 34831014, 2021). "Our results suggest that dual targeting of WNT5A and RhoA signaling is a more effective strategy for controlling the invasion of BRAF wild‐type and BRAFV600 mutated melanomas treated with a BRAF inhibitor than targeting either of the proteins individually." (PMID 33969605, 2021). "We detected frequent and common aberrations shared by the primary tumors and melanoma metastases on chromosome 7, where BRAF localizes, while CNGs on chromosome 1 bearing NRAS was a metastases-only feature." (PMID 34885093, 2021). "Although BRAFi/MEKi combination treatments produce impressive initial clinical responses in a subset of BRAF-mutant advanced melanoma patients, resistance to treatment rapidly emerges within a few months, rendering the therapy ineffective." (PMID 34771678, 2021). "Our recent findings indicated a role of the Rho/MRTF pathway in migration, invasion, and metastasis of aggressive human cutaneous melanoma, as well as in the acquired resistance of BRAF mutant melanoma cells to BRAF inhibitors." (PMID 33921974, 2021). "To examine the mechanisms underlying the observed responses, we treated the BRAFi-resistant PTEN impaired melanoma cells with BRAF and PERK inhibitors and checked the expression of apoptotic markers." (PMID 34282258, 2021). "The expression of SOX10, which is a negative regulator of EGFR expression, can be decreased in BRAF mutant melanoma cells, leading to enhanced EGFR signalling upon the inhibition of BRAFV600E." (PMID 34066022, 2021). "In melanoma, an inverse relation between BRAF inhibition and the expression of ECM genes has been described as a marker of de-differentiated drug-resistant cells." (PMID 33438577, 2021). "Further, oncogenic BRAF fusions are frequently identified in melanomas prior to drug treatment, and BRAF fusion-positive cancers show resistance to BRAF inhibitor drugs such as vemurafenib and dabrafenib." (PMID 34503137, 2021). "The coexistence of BRAF mutations and PTEN inactivation does not only promote melanogenesis but also alters the response to current targeted therapy in melanoma, leading to drug resistance." (PMID 34282258, 2021). "Unfortunately, although great initial responses were seen in human trials, melanomas treated with only a targeted BRAF inhibitor almost always recurred." (PMID 33555482, 2021). "In this work, we show that BRN2 acts as a tumor suppressor during melanoma initiation and progression in a BRAF-PTEN context since BRN2 and MITF regulate positively and negatively the transcription of PTEN, respectively." (PMID 34140478, 2021).
melanoma (continued). "A combination of PDL-1 inhibitor atezolizumab (tradename Tecentriq) with BRAF inhibitor vemurafenib (tradename Zelboraf) and MEK inhibitor cobimetinib (tradename Cotellic) was approved in 2020 for unresectable or metastatic BRAF V600 positive melanoma." (PMID 34698235, 2021). "It has been reported that ceritinib enhances the efficacy of trametinib, a MEK inhibitor, in BRAF/NRAS‐wt melanoma cell lines, which makes it plausible that ceritinib would not have any effect in BRAF‐mutated cells." (PMID 34058070, 2021). "We showed that similar to Usp9x KD, G9 treatment also decreased SOX2 levels in BRAF-mutant melanoma cells and MG132 treatment reversed the reduction of SOX2 by G9." (PMID 33613844, 2021). "Cotreatment of melanomas with BRAF inhibitors and obatoclax, an inhibitor BCL2 family member, overcomes resistance to BRAF inhibitors in BCL2A1-amplified cells." (PMID 34063141, 2021). "This research opens up avenues for the development of novel and potent IGF1R/IR inhibitors for patients with BRAF-mutant melanoma." (PMID 34831014, 2021). "In mouse models of BRAFV600 melanoma, blockade of either PD-1 or PD-L1 synergized with BRAF inhibitor monotherapy or dual inhibition of BRAF and MEK." (PMID 34025662, 2021). "In one study, treatment of BRAF-inhibitor (BRAFi)-resistant melanoma cells with a miR-1246 mimic demonstrated downregulation of p-ERK and reduced vemurafenib antiproliferative activity." (PMID 33807778, 2021). "Here, we found that molecular targeting of FASN in melanoma cells resistant to the BRAF inhibitor PLX4032 increased the sensitivity to the drug." (PMID 34068792, 2021). "This molecule exerted anti-melanoma effects on cells lines and cells isolated from patients including the ones derived from tumors resistant to BRAF inhibitors." (PMID 33431809, 2021). "On the other hand, the effect of an inhibition of BRAF-mediated signaling in melanoma was studied by co-administering WNT3A and PLX4720 (a BRAFV600E inhibitor)." (PMID 34577571, 2021). "BRAF inhibitors in combination with MEK inhibitors are recommended as the standard treatment for BRAF mutant advanced melanoma." (PMID 34290710, 2021). "Fang and colleagues recently described the relationship between tumor BRAF/NRAS mutation status, clinical characteristics and response to conventional therapy in patients with melanoma BM." (PMID 33578810, 2021). "The use of BRAF-inhibitor monotherapy (e.g., dabrafenib) in advanced BRAFV600E/K mutant melanoma is associated with the development of secondary skin neoplasms (such as cutaneous squamous cell carcinomas and keratoacanthomas)." (PMID 33921947, 2021). "Recent clinical trials have demonstrated a statistically significant increase of both progression-free survival (PFS) and overall survival (OS) in BRAF V600 melanoma patients treated with BRAF and MEK inhibitors." (PMID 33503876, 2021). "Another BRAF inhibitor, vemurafenib was tested as a monotherapy in a basket study of BRAF V600E non-melanoma cancers." (PMID 33671873, 2021). "Consistently with the retrospective findings, we found that bilirubin significantly inhibited the antitumor effect of vemurafenib in BRAF mutant melanoma cell lines and xenografts." (PMID 34222023, 2021). "This capacity of activating MAPK pathway also plays a role in protecting melanoma cells with RAC1 and BRAF mutations from apoptosis when treated with RAF inhibitors." (PMID 34827551, 2021). "Rac1P29s was found to confer resistance to BRAF/MEK inhibitors (BRAFi/MEKi) to melanoma cells, which can be reversed by SRF/MRTF inhibitor." (PMID 34079763, 2021). "These two independent cohorts of patients with ITMs demonstrate a lower rate of BRAF positivity than the expected rate of 50% for all melanomas." (PMID 32542563, 2021). "COX2 expression in melanoma cells seems to correlate with invasion depth, and the role of COX2 has been also implicated in tumor angiogenesis, BRAF resistance, and immune evasion during check-point inhibitor therapy." (PMID 34944793, 2021).
melanoma (continued). "Patients with advanced BRAFV600E mutant melanoma are eligible for targeted therapy with BRAF and MEK-inhibitors, with objective tumor response rates in up to 75% of the patients." (PMID 33669315, 2021). "We conducted a retrospective study to assess potential prognostic factors, especially outcomes according to administration of local (intracranial) treatment (LT) with surgery and/or radiotherapy for BM in melanoma patients receiving ICI or anti-BRAF therapy." (PMID 34503304, 2021). "To explore the anti-metastatic potential of DET and DETD-35, our team established a BRAF-mutant human melanoma lung-seeking clone that we named A375LM5IF4g/Luc." (PMID 33810045, 2021). "BRAF, a component of the MAPK signalling pathway, is mutated in approximately 40% of melanomas, and of these, approximately 90% are at codon 600 and involve the substitution of valine to glutamic acid." (PMID 33572972, 2021). "Mutations in key genes of the MAPK/ERK pathway, namely NF1, NRAS and BRAF, identify three main molecular subtypes of melanoma." (PMID 34698264, 2021). "This change in Ca2+ distribution can contribute to the actin-based shape change and PMCA4b induced switch in motility style of BRAF mutant melanoma cells." (PMID 33802790, 2021). "BRAF inhibitor (BRAF-I) therapy for melanoma patients is initially highly effective, but drug resistance greatly limits its application." (PMID 34729105, 2021). "In BRAF-mutant melanoma, combining BRAF/MEK inhibitions and immune checkpoint blockade shows a synergistic and potentially safe response and is currently being investigated, taking drug resistance mechanisms into consideration." (PMID 33918490, 2021). "An augmented dependency on mitochondrial respiration was described in melanoma cells that express high levels of PGC1α (peroxisome proliferator-activated receptor γ coactivator 1α—a master regulator of mitochondria) and the BRAF gene." (PMID 34064489, 2021). "Despite the association of NRAS-mutant tumors with CSD skin, it is reported that UV signature lesions (C>T and CC>TT) are prevalent in a similar proportion of NRAS- and BRAF-mutant melanomas." (PMID 34210801, 2021). "Since the identification of BRAF as an important oncogene in melanoma in 2002, new therapeutic options have been developed and successfully implemented." (PMID 33954019, 2021). "In the BRIM8 study, the adjuvant vemurafenib was evaluated in resected stage IIC-IIIA, IIIB and IIIC (BRAF V600+) melanoma patients." (PMID 34884176, 2021). "Further, miR-1246, which we found as strongly upregulated in melanoma cells in our study, is known to act as an oncogene in melanoma via influencing cell viability and migration and promoting BRAF inhibitor resistance." (PMID 34073664, 2021). "Trametinib (GSK1120212) has received FDA approval as a monotherapy for the treatment of unresectable/metastatic BRAF-mutant malignant melanoma and for the treatment of anaplastic thyroid cancer in combination with dabrafenib (a BRAF inhibitor)." (PMID 33546207, 2021). "These discoveries have led to the emergence of targeted drug treatments for melanoma, such as BRAF inhibitors, MAP2K7 (also known as MEK), and MAPK1 (also known as ERK)." (PMID 34105069, 2021). "BPTES appeared to re-sensitize otherwise resistant melanoma cells to BRAF inhibition, as well as cisplatin-resistant ovarian and breast cancer cells to chemotherapy, owing to their reliance on the glutamine metabolism." (PMID 33804114, 2021). "Mutations in MEK and ERK are less studied but have been noted in developmental disorders and in both naturally occurring neoplasms and in response to BRaf inhibitors as a mechanism for resistance when treating cancers such as melanoma." (PMID 34680208, 2021).